ICOS (inducible T cell costimulator)
Diseases named in the same sentence as ICOS in open-access papers (continued):
Sharing a sentence is not in itself a finding about the gene and the disease.
breast cancer (continued). "The expression of Treg-related genes involving Treg-suppressive function was largely unchanged between CD177+ and CD177− TI Treg cells in human breast cancer or ccRCC, with slight elevation of ICOS, TIGIT, and CTLA4." (PMID 34599187, 2021). "We found that the proportion of Treg cells expressing CD39 and ICOS, either alone or in combination was the same in patients with breast cancer and controls." (PMID 30254632, 2018). "Some SNPs in six immunological genes, BTLA, ITGAL, CTLA4, ICOS, PDCD1, and VTCN1 were reported as breast cancer risk mutations in previous studies." (PMID 27911271, 2017). "In vivo intratumoral administration of TLR7 ligands led to ICOS+ TApDC activation and tumor regression in an orthotopic mammary tumor model." (PMID 26042126, 2015). "In human breast cancer, in vitro neutralization of ICOS molecule blocked pDC-induced Treg expansion and reduced IL-10 secretion by memory TA-CD4+ T cells." (PMID 26042126, 2015). "In the study cohort, we genotyped five SNPs (rs11889031, rs10932029, rs4675374, rs10183087 and rs10932037) in ICOS gene among 609 breast cancer patients and 665 age-matched healthy controls." (PMID 21917182, 2011). "Thus, we predicted that ICOS gene polymorphisms might also be related to the risk of breast cancer." (PMID 21917182, 2011). "ICOS expression on Tregs in breast cancer also correlated with poor prognosis." (PMID 41474629, 2026). "As it has been well established, breast cancer is the so-called “cold tumor” that with the paucity of tumor T-cell infiltration, we suggest ICOS agonist mAbs might be of promising to promote the anti-tumor T-cell responses." (PMID 38127899, 2023). "However, little data is available on the expression pattern of ICOS and the role of ICOS in breast cancer." (PMID 38127899, 2023). "In this study, we found that ILC2s were activated by ST2 and ICOS upregulation in both the micro- and macrometastatic regions, thereby supporting the possibility that ILC2s are activated throughout the metastatic cascades of breast cancer cells in the lung." (PMID 35805039, 2022). "In addition, DPP4 and ICOS expression were positively correlated in both breast cancer cohorts." (PMID 40708008, 2025). "The activation of ICOSL/ICOS signaling may trigger the Th2-type responses, and thus negatively regulates the immune cell responses against tumors, which is responsible for the poor survival in breast cancer patients." (PMID 31143539, 2019). "Increased ICOS expression on CD4+ T‐cells of patients treated with anti‐CTLA‐4 therapies has been seen in non‐small cell lung cancer, bladder cancer, and breast cancer." (PMID 41474629, 2026). "The results showed that ICOS was highly expressed in gastric cancer cells AGS, MKN-45 and MGC-803 compared to normal cells; it was highly expressed in breast cancer cells MCF-7 and MDA-MB-231 compared to normal cells." (PMID 36855091, 2023). "To evaluate the antitumor potential of ICOS agonism, we treated EMT6 (syngeneic breast cancer model) tumor-bearing mice with an anti-mouse ICOS mAb [an Fc variant of 7E.17G9 mouse (m)IgG1]." (PMID 37593752, 2023). "Phenotypic analysis of the markers we identified by scRNAseq revealed that expression of CXCR6, ICOS, JAML, NK1.1, NKG2D, and PD-1 by Vγ4+ and Vγ6+ cells remains unaffected by mammary tumor conditioning." (PMID 36480166, 2023). "ICOSL binding by ICOS or OPN exerts opposing effects on breast cancer cell migration, which is induced by OPN and dominantly inhibited by ICOS." (PMID 36769264, 2023). "It has been found that ICOS mRNA in TIL is highly expressed in human gastric cancer tissues, colorectal cancer tissues, breast cancer, head and neck tumors, and lung cancer." (PMID 37850501, 2023). "For instance, increased expression of ICOS was observed on CD4+ T cells from peripheral blood and tumor tissues of patients receiving anti-CTLA4 therapy in several types of cancer, including breast cancer, lung cancer, and bladder cancer." (PMID 38127899, 2023).
breast cancer (continued). "In a mouse breast cancer metastatic model, for instance, the ICOSL is a receptor for OPN, interacting at a different domain than that used by ICOS." (PMID 36769264, 2023). "However, the role of ICOS in breast cancer remains largely unknown." (PMID 38127899, 2023). "Recently, we demonstrated that inducible T-cell costimulator (ICOS) shares its unique ligand (ICOSL) with osteopontin (OPN), and OPN/ICOSL binding promotes tumor metastasis and angiogenesis in the 4T1 breast cancer model." (PMID 35052731, 2021). "Inducible co-stimulator (ICOS) is a CD28-related molecule exclusively expressed on activated T cells and plays a critical role in modulating the immune response in breast cancer." (PMID 31143539, 2019). "In addition, studies have illustrated that CD4+ T‐cell ICOS expression increases in peripheral blood and tumor tissues of patients treated with anti‐CTLA4 for bladder cancer, breast cancer, and non‐small cell lung cancer." (PMID 38506253, 2024). "In a clinical study on breast cancer patients, MWA was found to significantly induce increased levels of ICOS+ activated CD4+ T cells and serum IFN-γ, indicating a multifaceted impact on the local and systemic levels beyond coagulation necrosis and protein degeneration." (PMID 37182153, 2023). "Additionally, ROC curves are generated for ICOS expression and TNBC subtypes of all breast cancers in order to verify this finding." (PMID 38127899, 2023). "Analysis of lung Vγ4+ and Vγ6+ cells in mammary tumor-conditioned lungs revealed that inhibition of ICOS, PD-1, or TIM-3 failed to alter the proportion of cells expressing IL-17A, IL-17F, TIM-3, or AREG." (PMID 36480166, 2023). "Our results indicated higher ICOS expression is significantly associated with favorable survival in triple-negative breast cancer (TNBC) patients, but not for all subtypes of breast cancer patients." (PMID 38127899, 2023). "Risk score also predicted expression of several immune checkpoints, including PD1, PDL1, PDL2, TIM3, CD28, ICOS, IL2RB, and 41BB, in TNBC patients, and its predictive value in these patients was similar to that observed in the overall breast cancer patient cohort." (PMID 32756008, 2020). "Investigation of Treg subsets in blood and primary tumor biopsies from breast cancer patients demonstrated phenotypic similarity between Treg fraction II in blood, corresponding to activated Tregs, and intratumoral Tregs with high expression of CTLA‐4, TIGIT, and ICOS." (PMID 34165864, 2022). "Also, we found that Tregs from luminal breast cancer patients showed a distinct pattern of highly expressed costimulatory and co-inhibitory molecules, including PD-1, CTLA-4, ICOS, GITR, OX40, and CD39, underscoring the value of these molecules as targets for immunomodulation." (PMID 32601304, 2020). "Also, our data predict that depleting Abs that target ICOS, GITR, and OX40 (such as the depleting anti-OX40 Ab MEDI646955) could be good candidate drugs for patients with luminal breast cancer." (PMID 32601304, 2020). "Indeed, ILC2-derived IL-33 promotes tumor formation and metastasis in breast cancer by upregulating Treg cells through inducible co-stimulator (ICOS)/ICOS ligand (ICOSL) interaction, whereas IL-33 also activates ILC2s to recruit eosinophils through ICOS/ICOSL interaction during lung inflammation." (PMID 32117199, 2019).
systemic lupus erythematosus (44 papers, 2006 to 2026). An autoimmune multi-organ disease typically associated with vasculopathy and autoantibody production. "The pharmacological inhibition of glutaminolysis with DON reduced the expression of the critical costimulatory molecule ICOS on lupus Tfh cells, in association with a reduction of autoantibody production and B cell differentiation markers." (PMID 40956613, 2025). "ICOS deficiency or antibody-mediated depletion of ICOS-expressing CD4+ T cells in SLE1 lupus mice results in diminished pathogenic TFH expansion, inhibited plasma cell generation, and a reduction in class-switched IgG autoantibodies." (PMID 29559975, 2018). "Autoimmunity in sanroque mice is associated with de-repression of ICOS mRNA, and dysregulated ICOS expression is also believed to underlie the increase in Tfh and autoimmune phenotype seen in the Sle1 lupus-prone mouse model." (PMID 30210496, 2018). "Meanwhile, during human systemic lupus erythematosus, ICOS:ICOSL interactions have been linked with aberrant, overproduction of class-switched MBCs." (PMID 27559335, 2016). "In addition, the suppression effect against glomerulonephritis in lupus-prone mice by nasal anti-CD3 treatment was found to be associated with a significant reduction in the percentage of IL-17 expressing CD4+ICOS+CXCR5+ T cells." (PMID 31597242, 2019). "Mice that have a single-amino-acid mutation in Roquin1 (a negative regulator of ICOS mRNA stability) demonstrate a spontaneous lupus-like phenotype that is accompanied by elevated numbers of Tfh cells expressing higher level of ICOS, IFN-γ OX40, and IL-21 and activated phenotypes of GCs." (PMID 30158933, 2018). "Mice with the Roquin mutation exhibited high ICOS expression, excessive Tfh formation and lupus-like pathology, however this was abolished if the mice were rendered SAP-deficient, consistent with a critical role for T cell/B cell collaboration in driving this pathology." (PMID 30210496, 2018). "The upregulation of miR-101a is consistent with the previous finding that miR-101a is upregulated in CD4+ T cells from sanroque mice, which develop lupus-like autoimmune syndrome as a result of loss of Roquin mediated-repression of the inducible T-cell co-stimulator (ICOS)." (PMID 21170274, 2010). "For example, different peaks in the ICOS locus showed increased accessibility in lupus AcTfh, naive, and cTfh cells." (PMID 39688922, 2024). "In systemic lupus erythematosus (SLE), expansion of ICOS+cTfh cells has been associated with the disturb of B cell development and higher autoantibody production." (PMID 35222430, 2022). "A recent study on lupus-prone mice further elucidated that the systemic inflammation in lupus critically depends on ICOS stimulation by DCs and CD11c+ macrophages via the induction of essential PI3K-mediated pro-survival signals in organ-infiltrating T cells." (PMID 31597242, 2019). "In sanroque mice, the number of Tfh cells is increased with the hyperactive ICOS signaling and excessive production of IL-21, leading to the development of spontaneous GC formation and lupus-like autoimmune phenotypes." (PMID 30123218, 2018). "ICOS expression has been found to be enhanced in CD4+ T cells from lupus patients compared to healthy donors and ICOS levels were higher in patients with nephritis than in those without nephritis." (PMID 27635407, 2016). "In a different study, DC ICOSL expression was correlated with kidney nephritis and proteinuria, as well as kidney-infiltrating T cells, in MRL.Faslpr (lupus-prone) mice, further implicating ICOS in promoting tissue inflammation during active SLE." (PMID 27559335, 2016). "Here miRNA101 suppresses expression of the ICOS (a costimilatory molecule on T cells), which is defective in sanroque model of lupus, leading to stimulation of autoreactive B cells and a lupus-like illness." (PMID 20485490, 2010). "Treatment of lupus model mice with anti-ICOS mAb resulted in reduced anti-dsDNA antibody in sera and renal pathology." (PMID 16563187, 2006).
systemic lupus erythematosus (continued). "Disrupted roquin in sanroque mice leads to over-expression of ICOS and IL-21 in T cells, unrestrained formation of follicular helper T cells, autoantibody production and lupus phenotype." (PMID 16563187, 2006). "Mechanistically, glutaminolysis may support lupus Tfh cells by promoting the expression of costimulatory molecules, especially ICOS." (PMID 40956613, 2025). "As BCL-6, IL-21, CD40L and ICOS are all critical regulators involved in the differentiation and maturation of Tfh cells, these findings are helpful for understanding the role that Tfh cells play in lupus." (PMID 35637283, 2022). "In lupus, RA and spondyloarthritis, associations were found of ICOS expression by Tregs with high disease activity, with non-response to therapy, increased autoantibodies, and pro-inflammatory cytokine production." (PMID 36450783, 2022). "ICOS was also shown to regulate extrafollicular Tfh cells that can induce B-cell differentiation into short-lived plasma cells, which then produce autoantibodies in a murine lupus model." (PMID 29988391, 2018). "Moreover, infiltrated ICOS+ T cells were shown to be in close contact with B cells in lupus kidneys." (PMID 27635407, 2016). "In lupus kidney samples, it was found that ICOS+ T and B cells which infiltrated the kidneys were in close contact, suggesting that T-B interactions may also take place in peripheral tissues." (PMID 24000287, 2013). "In addition, the anti-ICOSL monoclonal antibody pre-treatment has a therapeutic effect on joint inflammation in systemic lupus erythematosus patients, indicating that ICOS/ICOS-L blockade may be therapeutically beneficial in renal intestinal inflammation." (PMID 37628716, 2023). "Simpson and colleagues found that high frequency of peripheral blood TFH cells was detected in patients with active systemic lupus erythematosus (SLE) and Sjogren's syndrome (SS) and they also expressed ICOS, CXCR5, and PD-1." (PMID 21750724, 2011). "We found that patients with systemic lupus erythematosus (SLE), rheumatoid arthritis (RA), or Sjögren’s syndrome (SS) had significantly lower percentages of ICOS+ Tregs in the peripheral blood than did healthy donors (HDs)." (PMID 37843279, 2023). "A previous report showed that the expression of ICOS on the surface of CD4+ T cells and soluble ICOS in the peripheral blood of patients with systemic sclerosis and systemic lupus erythematosus are significantly increased." (PMID 35723338, 2022). "ICOS+PD-1+CXCR5+CD4+ T cells are correlated with the functional properties of Tfh cells and play a role in severe systemic lupus erythematosus (SLE)." (PMID 26517519, 2015). "In humans, ICOS expression on CD4 and CD8+ T cells has been shown to be elevated in lupus patients, while ICOS-L (B7RP1) expression is downregulated in peripheral blood memory B cells after cognate interaction with ICOS+ T cells in coculture systems." (PMID 24000287, 2013). "Consistent with a stronger TCR signaling in lupus Tfh cells, Icos message expression was higher in W.Yaa than in B6 Tfh cells, and it was decreased by DON in a similar pattern as ICOS protein expression." (PMID 40956613, 2025). "In addition, it is reported that ICOS/ICOSL contributes to T cell activation and humoral immunity promotion in systemic lupus erythematosus (SLE)." (PMID 36405702, 2022). "A detailed functional analysis of ICOS on peripheral blood T cells from patients with systemic lupus erythematosus (SLE) has not yet been reported." (PMID 16563187, 2006). "Similar to what was observed in the SRBC-immunized BALB/c mice, blocking ICOS signaling led to a significant decrease in number of both GC B cells (∼65% reduction, p<0.01) and Tfh (CD4+ CD44high CXCR5+Bcl6+) cells (∼70% reduction, p<0.01) in this spontaneous autoimmune model of lupus." (PMID 25101629, 2014).
systemic lupus erythematosus (continued). "The canonical pathways that were inhibited/decreased included the ICOS-ICOSL Signaling in T helper cells, and TGF-β Signaling, PKCβ Signaling in T lymphocytes, Systemic Lupus Erythematosus In T Cell Signaling Pathway, and STAT3 Pathway." (PMID 36032117, 2022).
Autoimmunity (41 papers, 2013 to 2025). The occurrence of an immune reaction against the organism's own cells or tissues. "Tfh cells typically express CXCR5, PD-1, and ICOS, and previous studies showed that upregulation of these markers in Tfhcells was associated with abnormally high autoantibody titers in autoimmune patients." (PMID 37901207, 2023). "T-cell function is highly dependent on miR-101 modulation of ICOS mRNA and a reduction in miR-101 mediated regulation can increase ICOS expression on naïve T-cells increases, causing an effector T-cell-like phenotype and that results in autoimmunity." (PMID 33995383, 2021). "Further, impaired IFN-γ production and reduced CD4+ and CD8+ T cell response was observed in ICOS-deficient patients leading to immunodeficiency and autoimmunity." (PMID 29892278, 2018). "Patients with antibody deficiency, autoimmunity, and combined immunodeficiency should be screened for ICOS mutations." (PMID 28861081, 2017). "We previously reported that protection from diabetes in ICOS−/− NOD mice was unexpectedly associated with the development of an autoimmune disorder of the neuro-muscular system, characterized by myositis and sensory ganglionitis." (PMID 28424681, 2017). "Thus, mechanistic dissection of a functional non-coding variant in human autoimmunity discloses a previously undefined pathway through which ICOS regulates Tph development and abundance." (PMID 38459032, 2024). "There is a clear understanding of the exacerbating role of ICOS+ Tregs in the disease in the immune-oncology field; however on the flip side, data are controversial in autoimmunity." (PMID 36591244, 2022). "While it has been shown that ICOSL is not required for B cell activation in LATm/m mice, we wanted to examine the requirement of ICOS in the development of spontaneous Tfh and autoimmunity." (PMID 33912184, 2021). "Inducible T cell co-stimulator (ICOS) deficiency has been categorized as a combined immunodeficiency often complicated by enteropathies, autoimmunity, lymphoproliferation, and malignancy." (PMID 31858365, 2020). "ICOS (inducible T cell costimulator) has an important but complex role in the induction of T cell anergy in vitro and the development of autoimmunity in vivo." (PMID 31266507, 2019). "Blocking the ICOS–ICOSL signaling with anti-ICOS antibodies can block or attenuate myocarditis resulting from autoimmunity." (PMID 29854842, 2018). "NOD mice deficient in the inducible costimulator (ICOS) and ICOS ligand (ICOS-L) spontaneously develop multifocal autoimmunity in the nervous system and in muscle tissues including spontaneous neuritis." (PMID 29179723, 2017). "In conclusion, while ICOS−/− or ICOSL−/− NOD mice are protected from T1D, they develop autoimmunity against neural and muscular tissues, indicating that ICOS-ICOSL interactions are important in polarizing NOD autoimmunity." (PMID 28424681, 2017). "In numerous murine models of autoimmunity, the inhibition of the function of Tfh cell-associated molecules, such as CD40 L, ICOS, and IL-21, has been shown to result in reduced autoantibody production." (PMID 23861861, 2013). "Given that Foxp3-specific ICOS ablation results in reduced numbers of Tfr cells, we investigated whether ICOS FC mice displayed signs of autoimmunity." (PMID 36754569, 2023). "Sanroque mice, in which the ICOS repressor is dysregulated, exhibit autoimmunity." (PMID 35157702, 2022). "The reason for the autoimmunity deviation from the pancreas to nervous tissue in the NOD.ICOS-/- and NOD.ICOSL-/- mice remains unknown." (PMID 35572553, 2022). "On the other hand, ICOS engagement by its ligand is essential for the generation, function and maintenance of Tfh cells that help germinal center formation and auto-antibody production in autoimmunity." (PMID 36591244, 2022). "Because ICOS activation is essential for terminal B cell differentiation and immune tolerance both ICOS and NF-κB deficiencies result in CVID-like immunodeficiency syndromes and autoimmunity." (PMID 31921101, 2019).